CXCL13 (C-X-C motif chemokine ligand 13)
Diseases named in the same sentence as CXCL13 in open-access papers (continued):
Sharing a sentence is not in itself a finding about the gene and the disease.
diabetic nephropathy (1 paper, 2025). "B Cell Trafficking in Diabetic Nephropathy: The upregulation of B cell chemokine CXCL13 in renal tissues of diabetic nephropathy (DN) patients provides a microenvironmental basis for B cell involvement in the disease." (PMID 40852718, 2025).
enteroviral infection (1 paper, 2017). "Concerning controls, CSF CXCL13 concentrations were elevated in two cases of varicella-zoster virus and one case of enterovirus infection, both of which were detected in the patients’ CSF by PCR." (PMID 28859668, 2017). "One patient with enterovirus infection also had a highly elevated level of CXCL13 (816.1 pg/ml) while the other 19 cases of enteroviral infection showed low CSF CXCL13 concentrations with a maximum of 29.3 pg/ml (median 5.8 pg/ml)." (PMID 28859668, 2017).
esophageal cancer (1 paper, 2025). A primary or metastatic malignant neoplasm involving the esophagus. "The Streptococcus genus enhances the antitumor immune response by increasing the infiltration of CD4+ CXCL13+ T cells, and the presence of Streptococcus in esophageal cancer can predict the response to anti‐PD‐1 therapy." (PMID 41346571, 2025).
gallbladder NET (1 paper, 2021). "The immunosuppressive TME in epithelial GC consist of infiltrating CD4+ T‐reg, CXCL13+ Th cells, CCL20lo/CD163hi, and APOE+ macrophages; however, it is the immune‐desert phenotype for gallbladder NET." (PMID 34185421, 2021).
glomerular disease (1 paper, 2024). "Thus TWEAK increases PLA2R expression in human podocytes, a response prevented by tacrolimus, while IL-17 drives the formation of kidney tertiary lymphoid organs in primary glomerular disease, a feature associated with high circulating CXCL13 levels." (PMID 39188767, 2024).
H1N1 virus infections (1 paper, 2017). "The H7N9, H7N7 and H5N1 infected mouse lung transcriptome also showed higher levels of CXCL13, IL-6, IFNG, IFNB1, IRF9, IRF1, and TNF compared with 2009 pandemic H1N1 virus infections." (PMID 28558796, 2017).
haemolytic anaemia (1 paper, 2025). "CXCL13 has been proposed as a potential biomarker of activity in SLE and LN, and CXCL13 and CCL4 were shown to have utility in SLE-related haemolytic anaemia, while their roles in NPSLE remain elusive." (PMID 40672966, 2025).
Helicobacter infection (1 paper, 2015). "CXCL13 plays an important role during the B-cell homing to follicles in lymph nodes and spleen and formation of gastric lymphoid follicles, and it is involved in the pathogenesis of Helicobacter infection." (PMID 25889172, 2015).
hidradenitis suppurativa (1 paper, 2025). A chronic suppurative and cicatricial disease of the apocrine glands occurring chiefly in the axillae in women and in the groin and anal regions in men. "The LTo gene program (including CXCL13 and FDCSP) was not expressed in healthy adult skin but could be upregulated in specific skin diseases, particularly hidradenitis suppurativa." (PMID 40993240, 2025).
histiocytic sarcoma (1 paper, 2020). An aggressive malignant neoplasm with a poor response to therapy, usually presenting as stage III/IV disease. "The false positive cases of the 3‐marker (CXCL13, IL‐10, and sIL‐2R) and 2‐marker (CXCL13 and IL‐10) algorithms were due to two cases of histiocytic sarcoma and metastatic brain tumor." (PMID 32314548, 2020).
hyperlipidemia (1 paper, 2018). "Our data also revealed that CXCL13 and IL-1Ra were more induced on the NOD background by hyperlipidemia." (PMID 30305306, 2018).
hypersensitivity pneumonitis (1 paper, 2022). Hypersensitivity pneumonitis (HP) is a pulmonary disease with symptoms of dyspnea and cough resulting from the inhalation of an antigen to which the subject has been previously sensitized. "The strong evidence for the crucial involvement of the CXCR5 : CXCL13 axis in lymphoid cell biology and in facilitating cell-cell interactions that promote lymphocyte infiltration fuels speculation of potentially successful immune-targeted therapies in patients with hypersensitivity pneumonitis." (PMID 36164329, 2022).
hypothyroidism (1 paper, 2024). Abnormally low levels of thyroid hormone. "In this study, utilizing MR analysis for the first time, we discovered that hypothyroidism can lead to changes in the expression levels of 26 plasma proteins, including CXCL13, VAMP1, and CXCL10, among which CXCL10 may mediate the impact of hypothyroidism on the risk of developing IPF." (PMID 39185418, 2024).
inflammatory demyelinating neuropathy (1 paper, 2019). "CXCL13 appears to be more specific for representing inflammatory demyelinating neuropathy compared with the previously demonstrated cytokines such as HGF, TNF-α and CCLs for several reasons." (PMID 31712675, 2019). "Our findings indicate that the detection of serum CXCL13 will be useful to specifically recognize inflammatory demyelinating neuropathies in human." (PMID 31712675, 2019). "Considering the potential role of SCs as APCs24, these findings suggest that the CXCL13/CXCR5-mediated local immune reaction involving SCs may contribute to the development of autoimmune reaction in inflammatory demyelinating neuropathy." (PMID 31712675, 2019). "Taken together, our findings indicate that CXCL13+ macrophages may contribute to the high serum of levels of CXCL13 in inflammatory demyelinating neuropathy patients." (PMID 31712675, 2019).
intracranial hypertension (1 paper, 2017). A finding characterized by increased cerebrospinal fluid pressure within the skull. "One patient had intracranial hypertension, no pleocytosis in CSF, no anti-Borrelia antibodies in CSF or serum, no other obvious diagnosis but elevated CXCL13 (204 pg/mL) in CSF." (PMID 28730535, 2017).
Japanese encephalitis (1 paper, 2013). A disease due to a virus transmitted by an arthropod). "It is known that TBEV, unlike to Japanese encephalitis and West Nile virus infections, induces CXCL13, a B-cell chemoattractant, in the CNS." (PMID 23805778, 2013).
kidney cancer (1 paper, 2025). Primary or metastatic malignant neoplasm involving the kidney. "Additionally, LAG3 CNV was associated with poor survival in PCPG and KICH; CXCL13 in kidney cancers (KIRC and KIRP) and MESO; LAYN in KIRP, SARC and LGG." (PMID 40076932, 2025). "Higher expression of LAG3, PDCD1, and TIGIT showed the worst survival outcome of anti-ICB therapy in kidney cancer indication drug resistance, whereas high LAG3 and CXCL13 expressions were associated with better survival of anti-PDL1 therapy in metastatic BLCA, indicating drug sensitivity." (PMID 40076932, 2025). "Alternatively, poor survival and recurrence of kidney cancers, ESCA, and LGG were found to be significantly correlated with the lower methylation in the promoter of CXCL13." (PMID 40076932, 2025).
lacrimal gland disease (1 paper, 2011). "The source(s) of the large amount of CXCL13 produced during the course of lacrimal gland disease remains under investigation." (PMID 22044682, 2011).
latent syphilis (1 paper, 2020). A stage of syphilis characterized by the serologic evidence of infection by Treponema pallidum without evidence of accompanying signs or symptoms related to the disease. "This suggests that the concentration of CSF CXCL13 has certain reference value for the treatment efficacy of latent syphilis with failure treatment." (PMID 33336020, 2020). "As per the area under curve of CXCL13 concentration in CSF to diagnosis the treatment failure of latent syphilis was 0.8838 (95% CI: 0.8245–0.9430, P < 0.01)." (PMID 33336020, 2020). "Multivariate binary logistic regression analysis shows that the concentration of CXCL13 in CSF and the initial serum TRUST titer ≥1:64 are the risk factors for predicting the treatment failure of latent syphilis." (PMID 33336020, 2020). "However, the relationship between CXCL13 concentration and latent syphilis is still poorly understood." (PMID 33336020, 2020). "We speculate that the level of CXCL13 in CSF may be a marker to detecting whether latent syphilis patients are centrally infected and monitoring the treatment effect." (PMID 33336020, 2020). "In this retrospective study, the relationship of CXCL13 concentration of CSF and serum with latent syphilis was assessed in patients with treatment failure and the change in CXCL13 concentration of CSF and serum after standard treatment in these patients investigated." (PMID 33336020, 2020). "The ROC curve analysis found that when the concentration of CXCL13 in CSF was 9.41 pg/mL, it had the greatest value in predicting whether there was any treatment failure of the latent syphilis, the sensitivity and specificity were 73.53% and 95.59%, respectively." (PMID 33336020, 2020). "We aimed to investigate the CXCL13 concentration of the serum and cerebral spinal fluid (CSF) in human immunodeficiency virus (HIV)-negative latent syphilis patients with treatment failure and explore the change in CXCL13 after treatment." (PMID 33336020, 2020).
liver dysfunction (1 paper, 2022). "However, we observed a significant correlation between preoperative CXCL10 levels and laboratory parameters of liver dysfunction (AST: Rs = 0.304, p = 0.001; bilirubin: Rs = 0.370, p = 0.001; ALP: Rs = 0.286, p = 0.002) as well as between baseline CXCL13 levels and CRP (Rs = 0.344, p = 0.001)." (PMID 36077611, 2022).
lymphocytoma (1 paper, 2018). "In our present study, all children in the possible LNB group with elevated CXCL13 had pleocytosis with mononuclear dominance suggestive for LNB and, in a majority of cases, facial nerve palsy and/or anti-Borrelia antibodies in serum and/or EM/ Borrelia lymphocytoma." (PMID 30083887, 2018).
malignant glioma (1 paper, 2022). A grade III or grade IV glioma arising from the central nervous system. "Public database analysis from the TCGA GBMLGG cohort was used to evaluate the CXCL13 expression in varying degree of malignant glioma." (PMID 35570844, 2022).
mastitis (1 paper, 2017). Inflammation of breast tissue during lactation or postpartum due to an obstructed duct or infection. "Another significant feature of the mammary host response was the significant enrichment of the DEGs involved in chronic inflammatory response (CXCL13, IDO1 and S100A8) that led to the mastitis phenotype." (PMID 28081235, 2017).
metabolic syndrome (1 paper, 2022). A cluster of metabolic risk factors for CARDIOVASCULAR DISEASES and TYPE 2 DIABETES MELLITUS. "Rifaximin treatment reduced serum levels of several proinflammatory interleukins (IL) such as IL22 and CCL20 in both groups of patients, while IL17 and CXCL13 were only reduced in patients without metabolic syndrome manifestations." (PMID 35165326, 2022).
microhematuria (1 paper, 2025). "Urinary biomarkers, including microhematuria, α1-microglobulin, and CXCL13, have been proposed as potential predictors of disease activity and remission likelihood." (PMID 40363910, 2025). "Urinary markers: Urine tests are sources of various proteinuria remission prognostic factors in MN, such as microhematuria, urinary levels of α1-microglobulin, urinary levels of CXCL13, and inflammation biomarkers." (PMID 40363910, 2025).
nasal polyps (1 paper, 2018). "In this context, it was shown that the chemokines CXCL12 (SDF-1 α) and CXCL13 (BCA-1) are present at elevated levels in nasal polyps." (PMID 29564208, 2018).
neutrophil leukemia (1 paper, 2023). "RNA-seq analysis of the Treg subpopulation from the murine CLL model revealed its unique phenotype characterized by upregulation of multiple factors, including Il10, Ifnγ, and the chemokines Ccl3/4/5 Cxcl13, which likely contribute to the neutrophil leukemia-supporting phenotype." (PMID 37817276, 2023).
ocular toxoplasmosis (1 paper, 2023). Ocular toxoplasmosis is an infection in the eye caused by the parasite, Toxoplasm a gondii. "In another study, patients with ocular toxoplasmosis displayed high levels of IFN-induced chemokines CXCL9 and CXCL10 and circulating chemokines CCL25, CCL11, CXCL12, CXCL13, and CCL2." (PMID 36755348, 2023).
Optic neuropathy (1 paper, 2022). "Except for 2 of the patients with optic neuropathy, all patients had an AH CXCL13 level of more than 10 pg/mL." (PMID 38983560, 2022).
oropharyngeal tumors (1 paper, 2023). "It would be relevant to determine whether CXCL13 is also involved in the recruitment of B cells and T cells into oropharyngeal tumors in PD-1 blockade-responsive mice." (PMID 37035195, 2023).
osteonecrosis (1 paper, 2024). A none disease characterized by death of bone tissue due to a lack of blood supply. "The primary aim of the present study was to explore the potential correlation of serum / local CXCL13 expressions and disease severity in non-traumatic osteonecrosis of the femoral head (NT-ONFH)." (PMID 38429811, 2024).
pericarditis (1 paper, 2019). An inflammatory process affecting the pericardium. "CXCR3 and CXCL13 may serve as predictive markers of clinical manifestations, including pericarditis and arthralgia, in patients with AOSD." (PMID 31101882, 2019). "Furthermore, patients with pericarditis had higher CXCL13 grades than did those without pericarditis (p = 0.043)." (PMID 31101882, 2019).
peripheral nerve injury (1 paper, 2023). Injury to a peripheral nerve. "In addition, CXCL13, which is a chemoattractant for a subset of T cells, was reported to be induced in the DRG after peripheral nerve injury, contributing to neuropathic pain." (PMID 37660072, 2023).
peritonitis (1 paper, 2020). Inflammation of the peritoneum (tissue that lines the abdominal wall and covers most of the organs in the abdomen). "The Cxcl13+ FALC cover cell cluster was distinguished by the expression of the monocyte chemoattractants Ccl2 and Ccl7 and the neutrophil chemoattractants Cxcl1 and Cxcl10, suggesting a role for these cells in orchestrating the recruitment of inflammatory cells during peritonitis." (PMID 32294409, 2020).
pertussis (1 paper, 2022). A contagious bacterial respiratory infection caused by Bordetella pertussis. "There are obvious caveats to using CXCL13 as a biomarker for the longevity of pertussis vaccine-induced memory that need to be considered when designing clinical trials." (PMID 35211125, 2022). "From this work, we propose that CXCL13, circulating B. pertussis+ MBCs, and pertussis specific antibody titers should be evaluated further to determine their potential as biomarkers for pertussis vaccine-induced immunity." (PMID 35211125, 2022). "We also identified serum levels of CXCL13 and B. pertussis-specific MBCs as potential biomarkers of pertussis vaccine-induced immune memory." (PMID 35211125, 2022). "The data suggest that follicular responses, and in particular CXCL13 levels in sera, could be monitored in pre-clinical and clinical studies for the development of the next-generation pertussis vaccines." (PMID 35211125, 2022). "In this study we used numerous approaches to characterize the follicular response to pertussis vaccination including antibody titers to vaccine antigens, CXCL13 levels in sera, TFH cells, B. pertussis specific MBCs, and B. pertussis/PT specific bone marrow antibody secreting cells." (PMID 35211125, 2022). "Therefore, measuring CXCL13 levels post-vaccination using a minimally invasive blood draw could be utilized during clinical studies when testing candidate pertussis vaccines in humans." (PMID 35211125, 2022).
plasmacytoma (1 paper, 2022). Plasmacytoma is a localized mass of neoplastic monoclonal plasma cells that represents approximately 5% of all plasma cell neoplasms. "Notably, CXCL13 showed markedly increased expression within plasmacytoma tissues, suggesting that elevated CXCL13 levels may be associated with extramedullary disease." (PMID 36217194, 2022). "Finally, immunohistochemical analysis of BM biopsies from MM pts (n = 10), plasmacytoma samples (n = 10) and normal BM samples (n = 2) demonstrated the expression of CXCL13 in malignant plasma cells." (PMID 36217194, 2022).
Pleural effusion (1 paper, 2023). The presence of an excessive amount of fluid in the pleural cavity. "The relative expression level of CXCL13 was measured in the collected pleural effusions using Enzyme-Linked Immunosorbent Assay (ELISA)." (PMID 37025603, 2023). "Furthermore, the combination of VTQ and CXCL13 evaluation demonstrated high diagnostic value in differentiating benign and malignant pleural effusions." (PMID 37025603, 2023).
Pleuritis (1 paper, 2023). Inflammation of the pleura. "Amongst the TB pleuritis patients, IL-6 and CXCL13 had the highest fold decline as compared to the baseline levels." (PMID 36635313, 2023).
pneumococcal infection (1 paper, 2024). Infections with bacteria of the species streptococcus pneumoniae. "We observed that CXCL13 was dispensable for BRM formation, possibly due to the lack of persistent tertiary lymphoid structures after pneumococcal infections." (PMID 38715601, 2024).
pneumonitis (1 paper, 2025). An inflammatory process affecting the lung parenchyma. "Because the current cohort was small, unlike in the Spearman’s rank correlation coefficient analysis, neither the change in ICOS+CD4+ T cells nor in CXCL13 was identified as an independent risk factor for irAEs (or pneumonitis) in the multivariate analysis." (PMID 40198121, 2025). "An increased frequency of ICOS+CD4+ T cells was a better predictor for pneumonitis development than those of CXCL13 or IL-6 levels, and combined assessment of both changes in ICOS+CD4+ T cells and CXCL13 levels had an even greater predictive value for later development of pneumonitis." (PMID 40198121, 2025).
polyp (1 paper, 2026). A usually exophytic mass attached to the underlying tissue by a broad base or a thin stalk. "Similarly, in a separate study, CXCL13 (BCA‐1) was found to be significantly elevated in CRSwNP polyp tissue compared to control and CRSsNP inferior turbinate tissues." (PMID 41004123, 2026).
polyposis (1 paper, 2024). "Our analysis revealed distinct patterns: XCR1, CXCL13, and CXCR6 expression levels were diminished in M1-staged and advanced CRC cases, while CXCR6 expression was elevated in CRC patients with a history of polyposis, and CCR10 expression was heightened in lympho-invasive CRC." (PMID 39835121, 2024).
preeclampsia (1 paper, 2023). Preeclampsia is a hypertensive disorder of pregnancy that is characterized by new-onset hypertension with proteinuria presenting after 20 weeks of gestation, and depending on mild or severe forms may initially present with severe headache, visual disturbances, and hyperreflexia. "Dysregulation of eNOS and CXCL13 has been previously associated with adverse pregnancy outcomes such as PTB and preeclampsia." (PMID 37224249, 2023).
primary immunodeficiency (1 paper, 2021). "Interestingly, CXCL13, FCRLA, and PLA2G2D were also associated with primary immunodeficiency." (PMID 34395521, 2021).
prostatic diseases (1 paper, 2022). "Therefore, we speculated that CXCL13 may be a better predictor of prostatic diseases than PSA." (PMID 36613500, 2022).
retinal disease (1 paper, 2025). "The primary aim of the study was to investigate whether the highly sensitive SiMoA-established biomarker for NFL, GFAP and CXCL13 (representing neurodegeneration and -inflammation) could be detected in the bloodstream of patients with retinal disease." (PMID 40141267, 2025).
RSV bronchiolitis (1 paper, 2025). "The results showed that CXCL13 was an independent risk factor for the recurrence of wheezing in children with RSV bronchiolitis (95% CI 1.004–1.021, P < 0.05)." (PMID 41360931, 2025). "Plasma CXCL13 levels were also significantly higher in the RSV bronchiolitis group [258.76 (199.19, 354.66) pg/mL vs. 127.68 (82.43, 214.50) pg/mL; P < 0.001], as were plasma CCL13 levels [239.33 (125.11, 335.76) vs. 97.69 (54.38, 219.80) pg/mL; P < 0.001]." (PMID 41360931, 2025). "CXCL12 and CXCL13 may serve as biomarkers for assessing RSV bronchiolitis severity and predicting recurrence, aiding early clinical evaluation and prognosis." (PMID 41360931, 2025).